RN7SL745P (RNA, 7SL, cytoplasmic 745, pseudogene)
Gene: Miscellaneous RNA gene on chromosome 18 (23,004,564 to 23,004,862, forward strand). Ensembl gene ENSG00000242182.
Homologues: Orthologues: chimpanzee Metazoa_SRP (95% identical), macaque Metazoa_SRP (87% identical). Paralogues in human: RN7SL1 (76% identical), RN7SL2 (75% identical), RN7SL655P (74% identical), RN7SL3 (74% identical), RN7SL378P (74% identical), RN7SL597P (74% identical), RN7SL650P (74% identical), RN7SL660P (74% identical), RN7SL108P (74% identical), RN7SL296P (74% identical), RN7SL503P (74% identical), RN7SL218P (73% identical), and 700 more.